CADM1 (cell adhesion molecule 1)
Diseases named in the same sentence as CADM1 in open-access papers (continued):
Sharing a sentence is not in itself a finding about the gene and the disease.
lymphoma (14 papers, 2012 to 2025). A malignant (clonal) proliferation of B- lymphocytes or T- lymphocytes which involves the lymph nodes, bone marrow and/or extranodal sites. "Along these lines, CADM1-deficient mice develop lymphomas and to a lesser degree leukemias, as well as epithelial cell-derived adenomas spontaneously at increased incidences." (PMID 36270981, 2022). "Contrarily to solid tumors, nonsolid tumors such as mycosis fungoides and adult T-cell leukemia/lymphoma showed that high expression of CADM1 had an unfavorable clinical behavior." (PMID 34064472, 2021). "In this review, we focused on the role of CADM1 in the development of cutaneous malignancies and discussed the difference between cutaneous solid tumors and lymphomas." (PMID 33419290, 2020). "On the contrary to these cutaneous solid tumors except for Merkel cell carcinoma, cutaneous lymphomas, such as adult-T cell leukemia/lymphoma, mycosis fungoides, and Sézary syndrome, increase their CADM1 expression for the development of tumor environment." (PMID 33419290, 2020). "In mice experiments of the transplantation of lymphoma cells expressing CADM1, anti-CADM1 antibodies suppress the organ invasion of lymphoma cells, resulting in improved survival rates." (PMID 33419290, 2020). "More recently, cell surface expression of CADM1 has been described as an indicator of disease status and progression in some lymphoma subtypes." (PMID 31338332, 2019). "The tumor suppressor function of CADM1, however, extends beyond virus-induced lymphomas." (PMID 36270981, 2022). "Two out of five lymphoma patients also had CADM1+CD3+ PBMC with an OCI-flow > 0.7." (PMID 27893842, 2016). "We show for the first time that Cadm1 homozygous null mice die significantly faster than wildtype controls due to the spontaneous development of tumors at an earlier age and an increased tumor incidence of predominantly lymphomas, but also some solid tumors." (PMID 22553910, 2012). "Even though CADM1 was not required for the growth of LCLs in vitro, it might contribute to the absence of EBV-associated lymphomas in XLP-2 patients." (PMID 36270981, 2022). "However, the expression and functional roles of CADM1 in other viral-induced leukemias and lymphomas are not yet clear." (PMID 29698475, 2018). "However, the mechanistic role of CADM1-mediated leukemia/lymphoma cell proliferation and survival is not known." (PMID 25774694, 2015).
osteosarcoma (12 papers, 2018 to 2025). A usually aggressive malignant bone-forming mesenchymal neoplasm, predominantly affecting adolescents and young adults. "Although CADM1 is expressed in some normal tissues, studies in osteosarcoma have reported minimal toxicity with a CADM1-targeted ADC in in-vivo studies." (PMID 38895237, 2024). "More interestingly, ALPL, UNC5B, and CADM1 were also highly and specifically expressed in osteosarcoma compared with most normal human organs based on the TCGA and GTEx databases." (PMID 37457661, 2023). "The circular RNAs hsa_circ_0032462, hsa_circ_0028173, hsa_circ_0005909 regulate the Cell adhesion molecule 1 (CADM1) gene which is a co-expression mRNA functioning as a miRNA sponge in human osteosarcoma." (PMID 31301674, 2019). "Then we validated the expression of above circRNAs, miRNAs and CADM1 using Real-time qPCR in four human osteosarcoma cell lines and the human osteoblast cell line." (PMID 30153287, 2018). "In addition, CADM1 can be used as a biomarker for the differential diagnosis of osteosarcoma and chondrosarcoma." (PMID 34395444, 2021). "In addition, immunohistochemistry showed that 40 of the 49 cases of osteosarcoma (>80%) showed low expression of CADM1." (PMID 34395444, 2021). "The expression of three circRNAs and CADM1 over-regulated significantly in four human osteosarcoma cell lines compared to osteoblast cell line (p<0.05) and significant down-regulation could be seen in the has-miR-142-5p and has-miR-338-3p (p<0.05)." (PMID 30153287, 2018). "Ultimately, we found cell adhesion molecule 1 (CADM1) gene was not only a co-expression mRNA of the three mRNA expression profiles of OS, but also are predicted to be regulated by hsa_circ_0032462, hsa_circ_0028173, hsa_circ_0005909 by functioning as miRNAs ‘Sponge’ in human osteosarcoma." (PMID 30153287, 2018). "Further, three previously identified potential gene targets of ACT for osteosarcoma, including CADM1, CDH11, and MMP14, also showed high protein expression in osteosarcoma compared with normal adjacent tissues." (PMID 37457661, 2023). "miR-214-3p, targeting the CADM1 3′-UTR, inhibits CADM1 and activates the P44/42 mitogen-activated kinase (MAPK) signaling pathway, thereby promoting the invasion, migration, and proliferation of osteosarcoma." (PMID 34395444, 2021).
adult T-cell leukemia (11 papers, 2018 to 2025). "PAK2 amplification is frequently observed in Adult T-cell Leukemia/Lymphoma (ATLL) caused by T-cell lymphotropic virus, promoting CADM1-mediated interactions and enhancing the survival of ATLL cells." (PMID 40332759, 2025). "HTLV-1 is the cause of adult T-cell leukemia/lymphoma (ATLL), a CD4 + CD25 + CD62L + FoxP3 + CCR4 + CADM1 + effector memory T-cell lymphoproliferative disorder that accounts for 5% of T-cell lymphomas and leukemias." (PMID 35056532, 2021). "Interestingly, high CADM1 expression in Merkel cell carcinoma, adult T-cell leukemia/lymphoma (ATLL), mycosis fungoides, and Sezary syndrome is associated with poor prognosis." (PMID 34395444, 2021). "Next, we examined the interaction between CADM1 and CADM4 in cell spreading assay using a cell line, ATN1, which is derived from adult T-cell leukemia (ATL) expressing a high amount of CADM1 protein." (PMID 30131958, 2018). "Interestingly, CADM1 function differs in adult T-cell leukemia/lymphoma (ATLL), and NF-κB is thought to be involved in this process." (PMID 34395444, 2021). "Adult T cell leukemia/lymphoma (ATLL) tumor cells highly upregulate CADM1." (PMID 33419290, 2020). "On the other hand, interestingly, CADM1 is overexpressed in tumor cells of adult T-cell leukemia/lymphoma (ATLL) and involved in oncogenesis." (PMID 34574062, 2021). "There have been reports of overexpression of cell adhesion molecule 1/tumor suppressor in lung cancer 1 (CADM1/TSLC1), a member of the immunoglobulin superfamily, in HTLV-1-infected cells and adult T cell leukemia (ATL) cells." (PMID 36986415, 2023). "Researches revealed that CADM1 was upregulated in Kaposi’s sarcoma, HTLV-I-transformed cell and adult T-cell leukemia, small cell lung cancer, Merkel cell carcinoma, mycosis fungoides, Sezary syndrome." (PMID 37814227, 2023).
Obesity (10 papers, 2015 to 2025). Accumulation of substantial excess body fat. "Genome-wide association studies have identified SNPs in CADM2 (rs13078960, rs1307880) as obesity susceptibility loci, similarly with its related family member CADM1." (PMID 36986146, 2023). "In obese mice, expression of CADM1 and CADM2 increased, and Cadm1 loss protected mice from obesity." (PMID 29966015, 2018). "In addition, an increased association of obesity and T1D has also been reported; together, these findings may begin to suggest a possible link connecting alterations in CADM1 expression with increased body weight and the progression of autoimmune diabetes." (PMID 35133983, 2022). "Sik3, Apoa1, and Apoc3 have been shown to be associated with variations in total, HDL, LDL-cholesterol or triglyceride levels, and Cadm1 with obesity-related traits." (PMID 26555648, 2015). "Obesity risk variants were associated with increased CADM1 and CADM2 expression in the hypothalamus with a complex interplay of CADM1 and CADM2." (PMID 32373164, 2020). "Genome-wide association studies (GWAS) have indicated that gene polymorphisms in alleles of RAS p21 protein activator 2 (RASA2), cell adhesion molecule 1 (CADM1) and hypoxia inducible factor 1 alpha subunit inhibitor (HIF1AN) are associated with the risk of obesity." (PMID 29228687, 2017). "Such risk might be modified by specific polymorphisms of obesity-related genes such as RASA2 rs16851483, CADM1 rs12286929 and HIF1AN rs17094222, yielding some novel insights into breast carcinogenesis." (PMID 29228687, 2017). "Furthermore, the roles of ENG, FABP4, and CADM1 in critical biological processes such as vascular function, lipid metabolism, immunity, and adipose tissue regulation highlight the complex, and to some extent distinct etiology of childhood obesity from that of obesity presenting later in life." (PMID 41398348, 2025).
glioma (9 papers, 2012 to 2025). A benign or malignant brain and spinal cord tumor that arises from glial cells (astrocytes, oligodendrocytes, ependymal cells). "Nevertheless, the NGS genes PTPRS, MAP2, and CADM1 were expressed in most malignant cells across these gliomas, consistent with the observed neurological associations of these genes." (PMID 37693314, 2023). "CADM1 was proved to be a tumor suppressor which was downregulated in glioma tissues and most glioma cell lines." (PMID 32213181, 2020). "In glioblastoma, glioma-derived exosomal miR-148a promoted the proliferation and spread of glioblastoma cells via targeting CADM1 (cell adhesion molecule 1), thus activating STAT3 pathway." (PMID 31752198, 2019). "In addition, Cai, Zhu & Gong (2018) found that miR-148a regulated STAT3 pathway activity by directly targeting CADM1 to promote glioma cell growth and metastasis." (PMID 33062427, 2020). "It has been reported that the secretion of miR-1246 from exosomes, which binds to the mRNA of cell adhesion molecule-1 (CADM1) gene, was increased in malignant GBM and promoted the proliferation and migration of glioma cells." (PMID 34540663, 2021).
autism spectrum disorder (7 papers, 2012 to 2020). A spectrum of developmental disorders that includes autism, and Asperger syndrome. "CADM1 plays important roles in modulating synapse development and plasticity, and mutations in CADM1/Cadm1 gene have been associated with autism spectrum disorder." (PMID 29796015, 2018). "Mutations in the synaptic adhesion protein cell adhesion molecule 1 (CADM1) are also associated with autism spectrum disorder, a neurodevelopmental disorder of uncertain molecular origin." (PMID 25647412, 2015). "Mutations in the gene encoding the synaptic adhesion molecule CADM1 (RA175/Necl2/SynCAM1/Cadm1) have been identified in people with autism spectrum disorder (ASD) who have impaired speech and language." (PMID 22272290, 2012).
cervical disease (7 papers, 2017 to 2025). "Biomarkers with established diagnostic value in cervical disease have limited utility in the prediction of anal disease, with CADM1 identified as a marker with screening potential in a gay and bisexual men (GBM) population and MAL in HIV positive GBM population." (PMID 35241698, 2022). "Using prospective time-to-event data, we detected associations between CADM1-, DAPK1-, PAX1-, and RARB-related CpGs and cervical disease progression, and we identified novel progression-associated CpGs." (PMID 37932662, 2023). "In this study, we explored CADM1, MAL and miR124-2 DNA methylation using clinician-collected and self-collected HPV+samples from Papua New Guinea, a setting with a high burden of cervical disease." (PMID 38904134, 2024). "Methylation of CADM1, MAL, and miR124 has been related to the severity and duration of cervical disease." (PMID 31067838, 2019). "Host DNA methylation markers CADM1, MAL and miR124 have been identified in cervical disease, but not anal disease." (PMID 35241698, 2022).
liver cancer (7 papers, 2014 to 2023). An epithelial or non-epithelial malignant neoplasm that arises from the liver. "To investigate the correlation between miR-1246 and CADM1 expression, we analyzed these liver cancer tissue samples by RT-PCR and immunohistochemisty for miR-1246 and CADM1, respectively." (PMID 25159494, 2014). "It was also shown that down‐regulation of DLX6‐AS1 may inhibit the stem cell properties of liver cancer stem cells through upregulation of CADM1 by suppressing the methylation of the CADM1 promoter and inactivation of the STAT3 signaling pathway (D.‐M." (PMID 37042179, 2023). "Here, using clinical samples from 38 patients of liver cancer, we analyzed miR-1246 and CADM1 expression by RT-PCR and immunohistochemisty, respectively and found that miR-1246 expression was negatively correlated to CADM1, which was of statistical significance." (PMID 25159494, 2014). "In addition, in the liver cancer stem cells, DLX6-AS1 knockdown inhibited cell adhesion molecule 1 promoter methylation, which led to the inhibition of tumorigenesis." (PMID 31787849, 2019).
neuroblastoma (7 papers, 2006 to 2021). Neuroblastoma (NB) is the most common solid, extracranial childhood tumor. "Loss of CADM1 in chromosomes (11q23 region) is associated with a poor prognosis in neuroblastoma patients." (PMID 34395444, 2021). "Our observation that almost all the high-risk neuroblastomas examined highly expressed both HLA-E and CADM1 lends support for this hypothesis." (PMID 33968044, 2021). "CADM1 is known to be involved in inhibition of cell proliferation and induction of apoptosis with a reported loss of expression in a variety of cancers of epithelial cell origin such as breast, prostate, pancreatic, hepatocellular and colorectal cancer, but also in neuroblastoma." (PMID 24833255, 2014). "Clinicopathological analysis suggests that the CADM1 expression level is significantly related to the primary neuroblastoma stage and pathological type according to Shimada classification." (PMID 34395444, 2021). "CADM1 expression is significantly reduced in neuroblastoma and cancers of the lung, oesophagus and skin; furthermore, it is inversely correlated with cancer progression." (PMID 23063768, 2013). "Further functional studies are warranted to elucidate the role of CADM1 in neuroblastoma development and to investigate the possibility of CADM1 haploinsufficiency in neuroblastoma." (PMID 18559103, 2008). "Integration of the resulting candidate gene list with expression data of neuroblastoma progenitor cells pinpointed CADM1 as a compelling candidate gene." (PMID 18559103, 2008). "Meta-analysis indicated that CADM1 expression has prognostic significance and differential expression for the gene was noted in unfavourable neuroblastoma versus normal neuroblasts." (PMID 18559103, 2008). "On the other hand, neuroblastoma cells expressed CADM1, the ligand of CRTAM." (PMID 33968044, 2021). "Our study puts CADM1 forward as a strong candidate neuroblastoma suppressor gene." (PMID 18559103, 2008).
pulmonary emphysema (7 papers, 2014 to 2021). A subcategory of chronic obstructive pulmonary disease (COPD). "Increased CADM1 ectodomain shedding is a possible pathogenic mechanism shared by pulmonary emphysema and T2DM, two diseases caused by unhealthy lifestyle factors, such as smoking and poor diet." (PMID 24964098, 2014). "Considering that cigarette smoke is by far the most common etiologic agent for emphysema, oxidants in cigarette is likely to act as a critical inducer of CADM1 ectodomain shedding." (PMID 29892598, 2018). "In total of the treated and control mice of 30 weeks of age, Lm was positively correlated with the CTF and ADAM10 levels, and pan-cytokeratin was negatively correlated with CTF, suggesting an involvement of CADM1 shedding in emphysema progression." (PMID 29892598, 2018). "In conclusion, we showed that emphysema progressed in 12 weeks of smoking cessation after passive smoke exposure in C57BL/6 mice, in association with continuous increase in CADM1 shedding and drastic remodeling of alveolar septa." (PMID 29892598, 2018). "Increased CADM1 on mast cells has been identified in atopic dermatitis and pulmonary emphysema and has been shown to enhance nerve-mast cell interaction in a mouse model of trinitrochlorobenzene-driven contact hypersensitivity." (PMID 28158195, 2017). "We recently identified CADM1 shedding as a key event in the development of pulmonary emphysema, a representative chronic obstructive pulmonary disease characterized by alveolar wall destruction and enlarged air spaces." (PMID 26231557, 2015). "As the abundance of ICD molecules was sparse but present, increased CADM1 shedding appeared to contribute to the development of emphysema by generating αCTF and the ICD in lung epithelial cells." (PMID 26259600, 2015). "As reviewed here, CADM1 is involved in the development of pulmonary emphysema through its ectodomain shedding in lung epithelial cells by promoting the apoptosis of lung epithelial cells." (PMID 26636084, 2015). "αCTF contributes to the development and progression of emphysema as a consequence of increased CADM1 ectodomain shedding." (PMID 26259600, 2015). "In this review, we specifically focus on how CADM1 is involved in the development of pathological lesions in pulmonary emphysema and atopic dermatitis." (PMID 26636084, 2015). "Our results identify increased CADM1 ectodomain shedding as a molecular event shared by pulmonary emphysema and T2DM." (PMID 24964098, 2014). "This process may be a key event in the development and progression of emphysema in ex-smokers, because it can contribute to persisting inflammation, increased CADM1 shedding, and thereby defective alveolar regeneration." (PMID 29892598, 2018). "Taken together, persisting increase in ectodomain shedding of CADM1 appeared to contribute to the progression of emphysema in ex-smokers, and might be accounted for by alveolar septal remodeling." (PMID 29892598, 2018). "As shown in pulmonary emphysema, protease-over-antiprotease activity imbalance may be a precedent key event in lesions in which CADM1-expressing cell apoptosis occurs." (PMID 26231557, 2015). "We recently identified CADM1 shedding as a key event in the development of pulmonary emphysema." (PMID 24964098, 2014). "We recently found lung-epithelial cell adhesion molecule 1 (CADM1), also known as tumor suppressor in lung cancer 1 (TSLC1) and nectin-like molecule 2 (Necl-2), to be involved in the development of emphysema." (PMID 29892598, 2018). "In conclusion, the present study demonstrated a close link between increased CADM1 ectodomain shedding and increased AECII apoptosis in IIP and suggests a pathophysiologic commonality between IIP and pulmonary emphysema at the molecular level." (PMID 26231557, 2015). "Lung-epithelial cell adhesion molecule 1 (CADM1), an immunoglobulin superfamily member, is extracellularly shed to produce a proapoptotic C-terminal fragment (CTF) within the cell and contribute to the development of emphysema." (PMID 29892598, 2018).